FDFT1 (farnesyl-diphosphate farnesyltransferase 1)
Description:
Catalyzes the condensation of 2 farnesyl pyrophosphate (FPP) moieties to form squalene. Proceeds in two distinct steps. In the first half-reaction, two molecules of FPP react to form the stable presqualene diphosphate intermediate (PSQPP), with concomitant release of a proton and a molecule of inorganic diphosphate. In the second half-reaction, PSQPP undergoes heterolysis, isomerization, and reduction with NADPH or NADH to form squalene. It is the first committed enzyme of the sterol biosynthesis pathway.
Synonyms: SQS; SS; DGPT; ERG9; SQSD
Tractability: Small molecule: a drug acting on it is in phase 2 or 3 trials; a structure with a bound ligand is known; a high-quality ligand is known; it has a high-quality binding pocket; it belongs to a druggable protein family. Antibody: UniProt predicts a signal peptide or a membrane-spanning region. PROTAC: ubiquitination databases record sites on it; its protein half-life has been measured; a small molecule that binds it is known.
Target class: Enzyme; Transferase
Gene: Protein-coding gene on chromosome 8 (11,795,570 to 11,839,500, forward strand). Ensembl gene ENSG00000079459.
Subcellular location: Endoplasmic reticulum membrane
Subcellular location (Human Protein Atlas): Endoplasmic reticulum
Pathways (Reactome):
Metabolism: Activation of gene expression by SREBF (SREBP); Lanosterol biosynthesis; PPARA activates gene expression
Gene Ontology:
Molecular function: protein binding; squalene synthase [NAD(P)H] activity; transferase activity, transferring alkyl or aryl (other than methyl) groups
Biological process: cholesterol biosynthetic process; farnesyl diphosphate metabolic process; steroid biosynthetic process; lipid biosynthetic process; zymosterol biosynthetic process
Cellular component: endoplasmic reticulum; endoplasmic reticulum membrane; membrane; cytoplasmic side of endoplasmic reticulum membrane
Genetic constraint (gnomAD): Loss-of-function variants: 59 observed, 41.37 expected, observed/expected ratio (o/e) 1.43, 90% interval 1.15 to 1.76. The synonymous counts are far from expectation, so gnomAD's model fits this gene poorly and the ratio says little. Missense variants: 885 observed, 520.62 expected, observed/expected ratio (o/e) 1.7, 90% interval 1.61 to 1.8. Synonymous variants: 334 observed, 186.33 expected, observed/expected ratio (o/e) 1.79, 90% interval 1.64 to 1.94.
Homologues: Orthologues: chimpanzee FDFT1 (94% identical), macaque FDFT1 (94% identical), pig FDFT1 (92% identical), rabbit FDFT1 (91% identical), dog FDFT1 (89% identical), mouse Fdft1 (88% identical), guinea pig FDFT1 (86% identical), rat Fdft1 (81% identical), tropical clawed frog fdft1 (71% identical), zebrafish fdft1 (67% identical).
Diseases named in the same sentence as FDFT1 in open-access papers:
FDFT1 is named in the same sentence as 73 diseases in open-access papers, as found by Europe PMC text mining. Sharing a sentence is not in itself a finding about the gene and the disease. The quoted sentences say what the papers report.
lung carcinoma (13 papers, 2018 to 2025). "The present study examined the relationship between FDFT1 rs2645429 polymorphism and the risk of nonsmall cell lung cancer (NSCLC) in a population from southern Iran." (PMID 29765975, 2018). "Moreover, overexpression of CYP51A1, HMGCS1, and FDFT1 caused an increase in migration/invasion capabilities of cells in vitro, suggesting a positive association between these proteins and invasiveness of lung cancer cells." (PMID 35805888, 2022). "The important role of FDFT1 was also illustrated in ovarian cancer, colorectal cancer, and lung cancer." (PMID 35322581, 2022). "We confirmed the results of iTRAQ by western blotting with protein samples from sensitive and resistant brain and lung cancer cells and demonstrated that NCI677397 markedly increased the expression of FDFT1, HMGCS1, FDPS, and FASN." (PMID 38140768, 2024). "Furthermore, expression of HMGCS1 and FDFT1 was also reduced in lysates from KPLU compared to KPL tumours, providing additional evidence that Usp28 regulates Srebp2 in lung cancer." (PMID 37202505, 2023).
colon carcinoma (12 papers, 2020 to 2025). "Somatic variants revealed FDFT1 that frequently mutated only in the liver metastatic patients and targeting FDFT1 could be a feasible strategy in colon cancer, especially in the colorectal liver metastatic patients." (PMID 34046350, 2021). "It has been discovered that FDFT1 serves as a molecular target mediating the induction of ferroptosis by 3β-Hydroxy-12-oleanen-27-oic Acid (ATA) in colon cancer cell line HCT116." (PMID 40438588, 2025). "It has been reported that NAT8 is regulated by FDFT1 and promotes colon cancer cell proliferation in vivo and in vitro." (PMID 38517387, 2024). "High expression of FDFT1 was associated with patients at high risk of poor outcomes, establishing SQS and SQLE as accelerators for colon cancer cell proliferation and promoting tumor growth." (PMID 37509391, 2023). "For colon cancer, it has been shown that patients with high FDFT1 protein expression show significantly shorter overall and relapse-free survival than patients with low FDFT1 expression." (PMID 37958351, 2023). "In the HPA database, we found that the expression of AKR1C1, ALOX12, and CARS1 in colon cancer tissue is higher than normal tissue and the expression of FDFT1 in colon cancer tissue is lower than normal tissue by immunohistochemistry, which is consistent with our results." (PMID 34046350, 2021). "From the results of multiple studies, FDFT1 could act as an oncogene in some cancers but as a tumour suppressor in colon cancer." (PMID 33113804, 2020). "FDFT1 is significantly upregulated in ovarian cancer, prostate cancer, tongue squamous cell carcinoma, and glioma, in comparison to normal adjacent tissues, whereas its expression is comparatively low in colon cancer, gastric cancer, and renal clear cell carcinoma." (PMID 40438588, 2025). "However, ATP5MC3 and FDFT1 were protective genes for colon cancer patients." (PMID 34046350, 2021). "Conversely, lack of FDFT1 expression resulted in lower reactive oxygen species, inhibiting colon cancer cell proliferation due to the blockage of the pathway." (PMID 37509391, 2023).
colorectal cancer (11 papers, 2020 to 2024). A primary or metastatic malignant neoplasm that affects the colon or rectum. "A mutation of FDFT1 in liver metastasis of colorectal cancer is also related to liver metastasis." (PMID 33113804, 2020). "Recently, FDFT1 has been identified as a ferroptosis-related gene and is considered an important gene for prognosis prediction in colorectal cancer patients." (PMID 37834468, 2023). "In our study, the overexpression of FDFT1 decreased the level of Akt expression, which was consistent with a previous study in colorectal cancer." (PMID 35322581, 2022). "Farnesyl‐diphosphate farnesyltransferase 1 (FDFT1, squalene synthase) has been identified as a ferroptosis‐related gene, and it is considered an important gene for prognosis prediction in colorectal cancer patients." (PMID 35322581, 2022). "A study showed that downregulation of FDFT1 was correlated with malignant progression and poor prognosis in colorectal cancer." (PMID 34046350, 2021). "Conversely, the expression of FDFT1 was downregulated in most of the colorectal cancer (CRC) tumour tissues (19/23) but upregulated in most of the adjacent noncancerous tissues (18/23) and CRC cell lines." (PMID 33113804, 2020). "FDFT1 knockdown had the similar effects with GS in colorectal cancer and may become a promosing target of GS alternative methods." (PMID 34953498, 2021). "Two genes involved in ferroptosis and lipid metabolism, FDFT1 and HSPB1, have been related to a poor prognosis in colorectal cancer, which is congruent with our own findings in COAD metastases." (PMID 36582202, 2022). "We analyzed the correlation between stemness markers and cholesterol biosynthesis genes in TCGA colorectal cancer (COADREAD) cohort and revealed positive correlations between CSC markers (EphB2 and CD44) and cholesterol biosynthesis genes (HMGCR, HMGCS1, FDPS, and FDFT1)." (PMID 34621019, 2021).
prostate carcinoma (11 papers, 2009 to 2023). A carcinoma that arises from epithelial cells of the prostate gland. "Some of the identified mRNA isoforms are in genes already implicated in prostate cancer (includingLIG4,FDFT1 andRELAXIN), or in genes important in other cancers (e.g.NUP93 andMAT2A)." (PMID 30271587, 2018). "Therefore, the FDFT1 gene and its encoded enzyme, SQS, might become an important target in developing a pharmaceutical treatment for prostate cancer as an antineoplastic strategy." (PMID 37509391, 2023). "A recent study has shown how FDFT1 mRNA expression knockdown led to a significant decrease in prostate cancer cell proliferation." (PMID 37509391, 2023). "Previous studies addressed that the inhibition of FDFT1 significantly inhibited prostate cancer cell proliferation, reflecting the antitumor effects in prostate cancer development and its aggressive phenotypes by suppression of FDFT1 expression." (PMID 35322581, 2022). "FDFT1 transcript levels have been found to be significantly greater in prostate cancer tissues than in benign tissues, and higher in very aggressive cancers than in those that are moderately aggressive." (PMID 35093030, 2022). "In prostate cancer cell lines, inhibiting FDFT1 has been shown to inhibit cell proliferation." (PMID 35093030, 2022). "Downregulation of FDFT1 expression also inhibited prostate cancer proliferation." (PMID 34953498, 2021). "Downregulation of FDFT1 promotes malignant progression and worsens the prognosis of CRC,42, 43 whereas high FDFT1 expression results in enhanced invasion of prostate cancer." (PMID 37849388, 2023). "In addition, individuals who have prostate cancer have shown a significantly higher level of FDFT1 mRNA expression than non-cancerous specimens have." (PMID 37509391, 2023). "These included FDFT1, which is expressed at higher levels in human prostate cancer specimens and in aggressive cancers, and DHCR24, also known as seladin-1, an androgen regulated gene that is expressed significantly higher in prostate cancer and is positively related to T stage." (PMID 29156692, 2017).
Obesity (8 papers, 2009 to 2025). Accumulation of substantial excess body fat. "From our studies we can exclude FDFT1 rs7001819 as a susceptibility variant conferring risk to obesity in the Danish population." (PMID 19245693, 2009). "We aimed at replicating the observed association between the CTNNBL1 rs6013029 T-allele, CTNNBL1 rs6020846 G-allele, and FDFT1 rs7001819 C-allele and measures of obesity." (PMID 19245693, 2009). "Theprotein encoded by the FDFT1 gene is the first enzyme incholesterol biosynthesis, and studies have found that this gene can affect bloodlipids, blood sugar, and inflammation, thus participating in obesity-relatedcoronary heart disease, diabetes, and coronary artery calcification." (PMID 29658970, 2018). "The methylation site cg12568669 which was reported in the previous section to be associated with obesity also impacted blood pressure in a similar pattern, namely, by changing the expression of NEIL2 and FDFT1 genes." (PMID 37274792, 2023). "Further studies in obesity and breastfeeding through epigenetic changes in the FDFT1 gene can provide new insight." (PMID 37239458, 2023). "We found the methylation site, cg12568669 within FDFT1 gene contributes to obesity by changing the expression of FDFT1 and the nearby gene NEIL2." (PMID 37274792, 2023). "A recent GWA scan in 1,000 US Caucasians with measures available on BMI and fat mass, identified two novel obesity gene loci in the proximity of FDFT1 (farnesyl-diphosphate farnesyltransferase 1) and CTNNBL1 (catenin (cadherin-associated protein), β-like 1)." (PMID 19245693, 2009). "The gene was represented by other markers, however, none of these showed any association with obesity-related quantitative traits, suggesting that variants at the FDFT1 locus do not associate with obesity." (PMID 19245693, 2009). "The FDFT1 rs7001819 C-allele, on the other hand, did not associate with measures of obesity, neither in quantitative analyses nor in case-control studies." (PMID 19245693, 2009). "HMGCS1, NSDHL and FDFT1 encode 3-Hydroxy-3-methylglutaryl-CoA synthase, squalene synthase and NAD(P)H sterol dehydrogenase, respectively, which are all key enzymes involved in different steps of cholesterol biosynthesis and some of which are modulated in obesity." (PMID 30068314, 2018). "POC5, ILRUN, FDFT1, and NEIL2 mediated the impact of CpG sites on obesity through metabolic pathways." (PMID 37274792, 2023). "Integration of methylation data with gene expression profiles revealed putative mediators of these relationships—genes such as ILRUN, POC5, FDFT1, NEIL2, and others—whose methylation changes may affect metabolic pathways and contribute to obesity pathogenesis." (PMID 41303351, 2025).
ovarian carcinoma (7 papers, 2017 to 2024). A malignant neoplasm originating from the surface ovarian epithelium. "Interestingly, in cisplatin-resistant ovarian cancer cells, the expression of FDFT1 was found to be increased by sterol regulatory element binding transcription factor 2 (SREBP2)." (PMID 35008958, 2022). "They showed that USP32 and FDFT1 expression was higher in tumor spheroids than in adnexal cells, and that the FDFT1 inhibitor ZA, blocking USP32, or interfering with the mevalonate pathway might inhibit the formation of tumor spheres in epithelial ovarian cancer." (PMID 37679322, 2023).
breast carcinoma (6 papers, 2020 to 2025). "In conclusion, this study elucidated that VPA induced the ferroptosis of MDA-MB-231 cells via targeting FDFT1, representing a novel mechanism underlying its efficacy in potentially inhibiting breast cancer." (PMID 40438588, 2025). "Nevertheless, the underlying mechanism of FDFT1’s involvement in the progression of breast cancer and the facets of ferroptosis remains elusive." (PMID 40438588, 2025). "The involvement of FDFT1 in breast cancer progression through interaction with PGRMC1, a key protein in lipid metabolism, is considered to be a potential basis for breast cancer treatment." (PMID 35976950, 2022). "For TNBC, CD44, FDFT1, G6PD, and GLS2 were significantly associated with breast cancer grade (all p < 0.05)." (PMID 35154262, 2021). "In order to acquire an initial insight into FDFT1 expression patterns in human breast cancer, we screened TCGA databases via UALCAN and discovered that the expression of FDFT1 is reduced in breast cancer when constrasted with that observed in normal breast cancer." (PMID 40438588, 2025). "Thus, it is important to investigate the potential of VPA to trigger ferroptosis in breast cancer cells via targeting FDFT1." (PMID 40438588, 2025). "However, there have been scant studies in the domain of breast cancer research that have examined FDFT1." (PMID 40438588, 2025). "However, the effect of FDFT1 on breast cancer is still obscure." (PMID 40438588, 2025). "Consequently, the objective of this investigation was to investigate whether valproic acid inhibits the proliferation of breast cancer cells by enhancing ferroptosis, and to determine whether FDFT1 serves as a pivotal target in valproic acid’s mediation of ferroptosis in breast cancer cells." (PMID 40438588, 2025). "Furthermore, the levels of mRNA and protein for FDFT1 in the normal breast epithelial cell line MCF-10A, the ER-positive breast cancer cell line MCF-7, and the TNBC cell line MDA-MB-231 were determined via WB and qRT-PCR assays." (PMID 40438588, 2025). "Our investigation revealed that the expression levels of FDFT1 in breast cancer specimens were notably reduced when compared to those in normal tissues, with the lowest expression observed in triple-negative breast cancer." (PMID 40438588, 2025).
cataract (4 papers, 2020 to 2023). Partial or complete opacity of the crystalline lens of one or both eyes that decreases visual acuity and eventually results in blindness. "SCR rats that are genetically predisposed to cataracts are reported to have mutations in Lss and Fdft1, which encode lanosterol synthase and farnesyl diphosphate farnesyltransferase, respectively, and which, like Hmgcs1 and Idi1, are involved in the cholesterol synthesis pathway." (PMID 36477544, 2022). "On the other hand, SCR-C carries a specific combination of hypomorphic mutations of lanosterol synthase and FDFT1 (farnesyl-diphosphate-farnesyl-transferase-1) genes, and the mutation of the lanosterol synthase gene results in decreased cholesterol levels in the lens, causing cataracts." (PMID 32033321, 2020).
hyperlipidemia (4 papers, 2014 to 2023). "It has been suggested to treat hyperlipidemia with FDFT1 inhibitors." (PMID 37239458, 2023). "Inhibitors of FDFT1 have been suggested for the treatment of hyperlipidaemia." (PMID 32443666, 2020).
glioblastoma (3 papers, 2018 to 2024). The most malignant astrocytic tumor (WHO grade IV). "FDFT1 is lowly expressed in some cancers; however, researchers found that farnesyl diphosphate synthase (FDPS), a key enzyme in isoprenoid biosynthesis, plays a crucial role in maintaining stemness in glioblastomas." (PMID 35391801, 2022). "In this study, inhibiting FDPS but not FDFT1 significantly affected TS formation, suggesting that protein prenylation may be important for glioblastoma TS formation." (PMID 30333528, 2018).
hepatocellular carcinoma (3 papers, 2016 to 2025). A malignant tumor that arises from hepatocytes. "Further, it has been shown that rat and human hepatocellular carcinoma cells display increased mitochondrial cholesterol levels and HMGCR or squalene synthase (FDFT1) inhibition sensitizes those cells to mitochondria-directed chemotherapy." (PMID 26698156, 2016).
kidney cancer (3 papers, 2022 to 2024). Primary or metastatic malignant neoplasm involving the kidney. "CTSB and FDFT1 are associated with ferroptosis in pancreatic and kidney cancer, respectively." (PMID 36902448, 2023). "Huang and Zhang identified FDFT1 as a potential biomarker associated with ferroptosis in kidney cancer (KIRC), finding that FDFT1 upregulation inhibited cell proliferation, migration, and invasion, with potential antitumor effects occurring via the AKT signaling pathway." (PMID 39765715, 2024). "Furthermore, researchers have indicated that downregulated FDFT1 expression in kidney tumors could become a potential biomarker for kidney cancer diagnosis or therapies." (PMID 35322581, 2022).
pancreatic cancer (3 papers, 2021 to 2025). "In colorectal and gastric cancers,[12a,c] FDFT1 plays a protumoral role, but it plays an anti‐tumoral role in Tongue squamous cell carcinoma and pancreatic cancer.[12b,d] Our study systematically reveals that FDFT1 plays a protumoral role in HCC." (PMID 39899681, 2025). "Pancreatic cancer patients with high levels of FDFT1 expression show significantly shorter overall survival." (PMID 37958351, 2023). "Interestingly, in murine pancreatic cancer autochthonous model (Ptf1a-Cre; lox-stop-lox-KrasG12D/+; Trp53lox/+), CRISPR-Cas9 screening for targeting ca. 3000 metabolic genes identified Fdft1 as one of the most differentially dependent genes in vivo." (PMID 37958351, 2023).
pancreatic tumor (3 papers, 2021 to 2025). "Moreover, we showed that correlations between expressions of FTH1 and the ferroptosis regulators, FDFT1 and LPCAT3, may be linked to initiation of pancreatic tumors." (PMID 34711879, 2021).